LEP (leptin)
Diseases named in the same sentence as LEP in open-access papers (continued):
Sharing a sentence is not in itself a finding about the gene and the disease.
Obesity (continued). "In obese humans, adipocytokines, like leptin and adiponectin secretion by adipocytes is increased, which regulates inflammatory response, cartilage catabolic activity and bone remodeling, and is involved in the occurrence and development of obesity-induced osteoarthritis." (PMID 36575508, 2022). "Obesity causes a state of a chronic low-grade systemic inflammation, with elevated levels of certain circulating proinflammatory adipokines, such as TNF-α, IL−6, leptin, plasminogen activator inhibitor-1 (PAI-1), angiotensinogen, and CRP, as well as lower levels of adiponectin." (PMID 36555411, 2022). "In this study, unfavorable levels of circulating leptin induced by the low-carbohydrate/high-fat diet were completely reversed by FO supplementation, suggesting that the anti-obesity effects of n-3 PUFAs may be through regulating leptin resistance, leading to a reduction in body weight gain." (PMID 35565762, 2022). "In obesity, not only the nutritional status of the individual changes, but also concentrations of messenger molecules, such as leptin, adiponectin, resistin, visfatin, and others, which may directly affect Th2 cell function or indirectly inhibit Th2 cells by promoting Th1/Th17-biased inflammation." (PMID 35844529, 2022). "One way in which obesity may influence airway fibrosis in asthma is through the adipokine, leptin." (PMID 35610699, 2022). "Other studies in animal models have suggested that the impairment in the brain leptin transport is acquired rather than causal since it is developed secondary to obesity and may be reversible with weight reduction." (PMID 34523036, 2022). "In conclusion, increased levels of leptin, or leptin resistance, may be at least partly responsible for the oocyte abnormalities taking place under conditions of metabolic dysregulation during obesity." (PMID 36855701, 2022). "Intriguingly, many mouse models of obesity are still responsive to intracerebroventricularly delivered leptin with high sensitivity compared to peripheral infusion, indicating that impaired brain access via diminished BBB transport may contribute to leptin resistance and other biological conditions." (PMID 36131285, 2022). "Notably, adipokines may serve as a link between obesity and asthma, such as leptin, TNF-α, and IL-6." (PMID 36051916, 2022). "Identification of rare disease-causing variants (DCV) and rare variants with unknown clinical significance (VUS) in the leptin-melanocortin signalling pathway in participants with and without obesity." (PMID 35574020, 2022). "Furthermore, the suppressed expression of inflammatory factors, regulatory expression of catabolism genes including Srebf1, Pgc1a, Lxra, Hsl, Leptin, and Ppara; the modulatory effect of microbial diversity; and richness were responsible for the preventive mechanisms against obesity of OT." (PMID 35967777, 2022). "Consequently, suppression of leptin and resistin expressions is an alternative against obesity." (PMID 35806278, 2022). "Furthermore, this study revealed sex differences in response to leptin, indicating that increased leptin levels in obesity may affect males more than females." (PMID 35610699, 2022). "This mouse nonsense LEP mutation changes an arginine into a stop codon, producing a truncated protein, which is further degraded in adipocyte cells, thereby causing a lack of leptin production and, thus, obesity." (PMID 35563103, 2022). "Therefore, we speculated that hypothalamic EphA3 might play a protective role in preventing obesity, which may share some similarities with leptin resistance in the hypothalamus of obese mice." (PMID 37013864, 2022). "Moreover, serum leptin levels significantly correlated with these obesity markers, suggesting that circulating leptin may mediate the regulatory effects of estrogen signaling on adipose tissue homeostasis." (PMID 35757435, 2022).
Obesity (continued). "This suggests the putative role of leptin in programming, as the treatment with leptin in early life affected the establishment or maintenance of DNA methylation patterns and subsequent gene expression later in life, after an environmental challenge such as obesity." (PMID 36855701, 2022). "Such genetic variants in the leptin-melanocortin signaling pathway are the cause of rare genetic diseases of obesity, including proopiomelanocortin (POMC) deficiency and leptin receptor (LEPR) deficiency, which are characterized by early-onset severe obesity and hyperphagia." (PMID 35123544, 2022). "The question whether the leptin resistance observed in the hypothalamus is also observed in the thymus or whether other factors, such as adipogenesis of thymic tissue, are involved in obesity-related thymic hypofunction needs further clarification." (PMID 36685567, 2022). "In addition, it was speculated that leptin may affect obesity through modulating miR-27a circulating levels, but this mechanism needs more studies to be further explained." (PMID 35590121, 2022). "Inflammatory cells (T-lymphocytes, macrophages, neutrophils) and pro-inflammatory cytokines (IL-6, IL-8) which are implicated in the pathogenesis of endodontic infections, such as pulpitis and apical periodontitis, could be influenced by obesity and leptin levels." (PMID 35216099, 2022). "In obesity, hyperleptinemia may emerge as a compensatory mechanism to control leptin resistance." (PMID 36422274, 2022). "This association may reflect the lack of leptin suppression by catecholamines in obesity, which occurs in the dependence of β1- and β2-adrenergic receptors in healthy human adipocytes." (PMID 36074318, 2022). "Hence, improvements in central leptin sensitivity could be effective in tackling for general obesity." (PMID 35909571, 2022). "Notably, peripheral ghrelin and leptin have been increasingly used as biomarkers for obesity." (PMID 35634372, 2022). "In addition, leptin has been suggested as an intermediate link between obesity and breast cancer." (PMID 36292657, 2022). "FDA approval has been given, however, to metreleptin, an analog of leptin, for treating lipodystrophy because of its proven efficacy in treating leptin deficiency disease compared to its lack of efficacy in treating common obesity with hyperleptinemia." (PMID 35527735, 2022). "We hypothesize that the group of pre-pubertal children with obesity and with low z-scores of circulating leptin levels could possibly benefit from treatment with Metreleptin in terms of an improvement in parameters of liver metabolism and potentially also weight loss." (PMID 35677722, 2022). "The physiology-dependent mechanism believes that the physiological components of obesity, including blood sugar control, insulin action and leptin signaling, may lead to respiratory disturbances and increased central sleep apnea by reducing chemical sensitivity." (PMID 35923456, 2022). "Leptin may increase the proliferation of keratinocytes and the secretion of pro-inflammatory proteins that are characteristic of psoriasis, while the secretion of adiponectin, supposedly anti-inflammatory, is reduced in obesity." (PMID 35806402, 2022). "Interestingly, although LEP heterozygosity was associated with higher metabolic efficiency and longevity in mice, such an effect was not assigned in humans, despite patients with LEP mutations showing the expression of more severe phenotypes of obesity." (PMID 35563103, 2022). "Therefore, obesity could be the reason for the increased serum leptin in participants who sat longer in our study." (PMID 36698957, 2022). "Interestingly, serum leptin levels have been found elevated in patients with asthma compared with healthy controls, an observation suggesting that leptin may contribute to the pathogenesis of the disease by obesity-independent mechanisms." (PMID 35807067, 2022).
Obesity (continued). "Therefore, while subcutaneous leptin administration may mimic increased systemic leptin levels present in obesity, it may be insufficient to elucidate the direct effects of leptin on the lungs." (PMID 35610699, 2022). "However, the majority of obesity in humans is not the result of leptin deficiency, but rather of leptin resistance—a critical barrier to leptin therapy." (PMID 35527735, 2022). "However, exogenous leptin therapy lacks efficacy due to obesity-induced leptin resistance." (PMID 36297523, 2022). "Furthermore, it has been suggested that a defect in this pathway could explain the simultaneous resistance to the appetite-suppressing effects of leptin and insulin in obesity." (PMID 35563589, 2022). "Furthermore, IL10 shares a similar structure and function with leptin, and over-expression of murine IL10 in skeletal muscle by adeno-associated virus (AAV) transfer meliorated hyperphagia, obesity, glucose intolerance, and insulin resistance in leptin deficiency mice by substituting for leptin." (PMID 35715850, 2022). "Furthermore, BioT influenced the risk of this cancer independent of obesity whilst a similar trend was detected for leptin." (PMID 36558416, 2022). "Therefore, we hypothesised that enhanced circulating leptin concentrations, particularly in subjects with obesity or type 2 diabetes mellitus, may contribute to several comorbidities, such as renal injury or cardiovascular disease." (PMID 35806353, 2022). "We examined multiple factors associated with obesity and metabolic dysfunction, including extent of weight loss, adiposity, mammary fat pad adipocyte size, and local or circulating leptin levels; none were associated with changes in tumor burden in formerly obese mice." (PMID 35775614, 2022). "Therefore, majority of the stress responses mediated via the HPA/I axis are conserved across vertebrates, except for adipostasis, which may be related to the unique roles of leptin signaling in the control of obesity in zebrafish." (PMID 35937837, 2022). "However, it has been reported that during obesity, the levels of circulatory leptin increase." (PMID 35159361, 2022). "In general, LEP mutations may result in a lack of or smaller amounts of leptin, as well as its altered production, whereas exogenous administration of leptin is able to restore a normal health state in obesity." (PMID 35563103, 2022). "Inflammatory processes linked to obesity occur in both vascular and non-vascular tissues, and endothelial cells are activated by the vasoactive chemicals secreted by adipocytes, such as resistin and leptin." (PMID 36299943, 2022). "Increased leptin and leptin receptor (ObR) levels and decreased APN levels were reported in obese patients with GERD, and increased leptin levels, widely considered as a marker of obesity, have been associated with frequent GERD symptoms and clinical and endoscopic severity of GERD." (PMID 35409299, 2022). "The mechanism by which leptin is elevated in the postnatal pups under normal conditions and augmented by early overnutrition should be further investigated as it may provide important insights into the developmental programming of adult obesity." (PMID 34475504, 2022). "Thus, vitamin D depletion might increase appetite and lead to obesity by directly regulating leptin expression." (PMID 35721764, 2022). "In suggesting that leptin may be the biochemical “link” connecting obesity, diabetes, and cognitive impairment, it seems necessary to comment on the seeming paradox regarding the observation that both mid-life obesity and late-life weight loss are considered risk factors for developing AD." (PMID 35527735, 2022).
Obesity (continued). "We observed that pre-pubertal children with obesity and with steatosis hepatis have significantly lower z-scores of circulating leptin levels than children with an unremarkable liver sonographic finding, and z-scores of circulating leptin levels correlate negatively with degree of steatosis hepatis." (PMID 35677722, 2022). "Thus, leptin is a key molecule in obesity-induced T cell phenotypic changes." (PMID 36685567, 2022). "Notably, inoculation of 5TGM1 MM cells into ob/ob mice, a genetically-induced model of obesity resulting from leptin deficiency, did not promote tumour growth." (PMID 35908046, 2022). "Overall, existing evidence suggests that leptin methylation could link obesity and OA development." (PMID 35873487, 2022). "Consequently, leptin administration is inefficient for the treatment of obesity." (PMID 35742928, 2022). "Additionally, elevated levels of leptin also modify the vasomotor function in obesity." (PMID 36299943, 2022). "Importantly, hyperleptinemia and leptin resistance are common in obesity disease." (PMID 35203274, 2022). "In addition, leptin can also be produced by bone marrow adipocytes and if reaching high local concentration, it stimulates myeloid differentiation which can promote leukocytosis often found in obesity." (PMID 36405720, 2022). "However, increased leptin concentrations in cats have been associated with insulin resistance independent of obesity and in the current study there was not a significant difference in BCS between remission and control cats." (PMID 35968003, 2022). "Adipokines, including leptin, adiponectin, resistin and visfatin, secreted from adipose tissue and elevated in obesity, as well as cytokines and chemokines, contribute to the pathophysiology of obesity-related disorders, especially to type 2 diabetes mellitus development." (PMID 35624760, 2022). "Thus, we can hypothesize that impaired leptin signaling in obesity and more specifically in NK cells might contribute to the dysregulation of the mTOR pathway." (PMID 36569860, 2022). "However, based on some studies in humans and animals, it is thought that the hyperleptinemia state in patients with obesity may eventually induce leptin resistance." (PMID 35795152, 2022). "Furthermore, helping to minimize obesity, the ability of melatonin to alter subjective hunger and desire to eat, plus influencing plasma leptin, may regulate food intake." (PMID 36562040, 2022). "Furthermore, leptin levels were also shown to increased in the follicular fluid of obese women, suggesting that ovarian follicular environment mirrors the systemic alterations seen during obesity." (PMID 36855701, 2022). "Therefore, at the neuronal level leptin indicates the degree of obesity of an organism." (PMID 35159361, 2022). "Researchers found that NLRP3-related inflammation was activated in the fat pads of leptin-deficient mice and high-fat diet-fed obese mice and that NLRP3-dependent caspase-1 activation in hypertrophic adipocytes may induce obesity and adipocyte death through pyroptosis." (PMID 35677632, 2022). "In adults, leptin is positively correlated with fasting insulin concentrations and is a predictor of glucose intolerance, insulin resistance and MetS regardless of underlying obesity." (PMID 35743665, 2022). "Future research into methods to treat obesity in Asia will need to take into account the potential effectiveness of bariatric surgery and the recent development of new, hormone-modulating drugs being developed to counter leptin resistance and ghrelin imbalances." (PMID 36143948, 2022). "Genes encoding leptin (LEP), leptin receptor (LEPR), melanocortin 4 receptor (MC4R), proprotein convertase subtilisin/kexin type 1 (PCSK1), proopiomelanocortin (POMC), kinase suppressor of ras 2 (KSR2), adenylate cyclase 3 (ADCY3), and others contribute to the development and progression of obesity." (PMID 36141228, 2022).
Obesity (continued). "Moreover, a growing body of data has suggested that elevated serum leptin levels may play a role in the increase in insulin resistance in obesity." (PMID 35355566, 2022). "The authors suggested that the leptin-cortisol relationship may be important for understanding the neuroendocrine starvation response, and that poor system control may ultimately contribute to obesity." (PMID 35480480, 2022). "It is also relevant in line with circadian dysregulations related to the obesity condition, such as reduced locomotor activity, alterations in glucose regulation, oxidative stress, leptin, and ghrelin signaling, as well as hepatic lipid dysregulations that may be linked to metabolic disorders." (PMID 35990356, 2022). "In early obesity, the establishment of a rapid hyperleptinemia and increased leptin signalling may affect ovarian function particularly through the negative impact on folliculogenesis, altered steroid synthesis and secretion in the growing follicle, and oocyte maturation." (PMID 36855701, 2022). "Thus, it has been hypothesized that obesity and insulin resistance cause TSH secretion to rise as a result of leptin signaling, which causes thyroid volume expansion and nodule formation." (PMID 36439513, 2022). "Hence, under conditions of dysregulated leptin signalling (hyperleptinemia or resistance) during the course of obesity, leptin may well negatively impact the establishment of the epigenetic programme, affecting oocyte development and growth." (PMID 36855701, 2022). "In subjects with obesity, elevated leptin levels in blood are not paired by proportionally high leptin levels in the cerebrospinal fluid, suggesting a causal relationship between a deficit in the transport system that carries leptin to the CNS and obesity." (PMID 34523036, 2022). "Additionally, the lack of insulin secretion after fructose ingestion also reduces leptin secretion by adipocytes, which may increase food intake, leading to weight gain and obesity." (PMID 35380611, 2022). "Mutations in the LEP gene may result in different obesity forms, e.g., congenital leptin deficiency and extreme obesity, caused by a lack of leptin or an altered circulating form of leptin with no biological activity." (PMID 35563103, 2022). "However, further insights revealing new genetic loci associated with obesity, influencing the circulating levels of leptin mediated or not by BMI are required." (PMID 35563103, 2022). "Changes in the production of adipokines such as leptin, resistin, lipocalin 2, tumor necrosis factor-α, chemerin, retinol binding protein 4, and interleukin-6 have been reported in obese individuals, and this can lead to the development of obesity-related metabolic diseases." (PMID 33498329, 2021). "Therefore, leptin activity by leptin long-lasting super active antagonist’s dysregulation in patients with obesity might contribute to high mortality rates in these patients during SARS-CoV-2 infection." (PMID 34220807, 2021). "Secondly, PTP-1B (protein tyrosine phosphatase 1B) was shown to mainly have adverse effects on leptin transduction and insulin signaling, and the inhibition of this enzyme is reported to speed up the insulin signaling pathways and in turn have positive effects in treating obesity." (PMID 34071722, 2021). "Elevated levels of leptin are related to obesity, and obese people may exhibit leptin resistance." (PMID 33842335, 2021). "Therefore, the use of angiotensin receptor blockers on obesity in a clinical setting could restore central leptin sensitivity, whose downstream results could enhance BAT activity." (PMID 34208585, 2021). "Higher leptin levels in osteoarthritic joint and expression of receptors for leptin on the surface of cartilage cells lead to the hypothesis that leptin may play a role in the cartilage degeneration in OA and may be the key molecule linking obesity to OA." (PMID 34440223, 2021).